MAD2L1 (mitotic arrest deficient 2 like 1)
Diseases named in the same sentence as MAD2L1 in open-access papers (continued):
Sharing a sentence is not in itself a finding about the gene and the disease.
lung adenocarcinoma (14 papers, 2016 to 2025). A carcinoma that arises from the lung and is characterized by the presence of malignant glandular epithelial cells. "Lung adenocarcinoma patients have a higher risk of cancer relapse and shorter recovery times, due to the elevated expression of MAD2L1 and CDK1." (PMID 36497125, 2022). "Of these, all except for MAD2L1 have a precedence of mutation in the Lung Adenocarcinoma TCGA Pan Cancer atlas." (PMID 33604163, 2021). "Studies have found that MAD2L1 is overexpressed in lung adenocarcinoma tissues, and the overexpression of MAD2L1 may indicate poor prognosis and increased risk of tumor recurrence in patients, which can be used as a prognostic marker for lung adenocarcinoma." (PMID 34126961, 2021). "Knockdown assays using siRNAs revealed that ANLN and MAD2L1 facilitated the malignant transformation of lung adenocarcinoma cells." (PMID 40723231, 2025). "miR-139-5p attenuates the growth, invasion and migration of lung adenocarcinoma cells by targeting MAD2L1." (PMID 34838000, 2021). "Further, multivariate cox regression analysis identified NDC80 and MAD2L1 as independent prognostic indicators in lung adenocarcinoma (LUAD) and squamous cell carcinoma (LUSC) respectively." (PMID 32795325, 2020). "Multiple types of human cancers, including lung adenocarcinoma, colorectal cancer, cervical cancer, HCC, acute T-cell lymphoma, breast cancer, and stomach cancer are closely associated with MAD2L1." (PMID 36637946, 2023). "The expression profile of NDC80 and MAD2L1 was analyzed in various tumors using GEPIA and we discovered that both NDC80 and MAD2L1 were broad-spectrum up-regulated in multiple human tumors including lung adenocarcinoma and lung squamous cell carcinoma." (PMID 32795325, 2020).
hepatocellular carcinoma (12 papers, 2017 to 2026). A malignant tumor that arises from hepatocytes. "Furthermore, miR-200c-5p suppresses proliferation and metastasis, inhibiting MAD2L1 (mitotic arrest deficient 2 like 1) in hepatocellular carcinoma." (PMID 37887350, 2023). "Furthermore, CCNB2, MAD2L1, BUB1, and NCAPG are significantly upregulated in hepatocellular carcinoma (HCC) tissues and are implicated in the growth and metastasis of HCC cells." (PMID 32265985, 2020). "Adopting a series of bioinformatics analysis methods, the current study identified 763 DEGs and seven hub genes (CDC20, CDK1, MAD2L1, BUB1, BUB1B, CCNB1, and CCNA2) that may be involved in hepatocellular carcinoma tumorigenesis and progression." (PMID 33767726, 2021).
breast tumor (6 papers, 2007 to 2025). "For example, subgroup 10 gathered breast tumours in which the GSTP1 and SERPINB5/maspin as well as the MAD2L1 and MYC genes, which specify basal-type adenocarcinomas, were over-expressed." (PMID 17338809, 2007).
colon cancer (6 papers, 2006 to 2025). "MAD2L1, a component of the mitotic spindle assembly checkpoint, was reportedly involved in cell cycle progression of colon cancer cell lines, since siRNA‐mediated knockdown induced a reduction of the cells in the S and G2/M phases." (PMID 40022573, 2025). "MAD2L1 expression is significantly higher in colon cancer tissue and cell lines compared to adjacent epithelial tissue and normal intestinal epithelial cell lines." (PMID 39272991, 2024). "MAD2L1 is highly expressed in colon cancer according to biological information." (PMID 32153633, 2020). "Conversely, we found that 6 genes involved in the mitotic spindle checkpoint (TTK, BUB1, BUB3, CDC20, MAD2L1, and BUB1B) are overexpressed in colon cancer specimens." (PMID 16919171, 2006). "Moreover, the expression level of MAD2L1 was significantly increased in CRC, and knockdown of MAD2L1 suppressed colon cancer cell growth by impairing cell cycle and apoptosis progression." (PMID 32153633, 2020). "MAD2L1 shows higher expression levels in CRC, is involved in colon cancer cell growth and cell cycle progression, and could be used as a new biomarker since it has a significant meaning for clinical treatment." (PMID 32153633, 2020).
prostate carcinoma (5 papers, 2016 to 2026). A carcinoma that arises from epithelial cells of the prostate gland. "At the same time, Mad2L1, a gene associated with dormant prostate cancer cells, may be used as a biomarker for prognostic survival." (PMID 35305591, 2022). "Gene set enrichment analysis revealed an association between DENND2D expression and the negative regulation of MYC target genes, including MAD2L1, ERH, and CLNS1A, which are overexpressed in prostate cancer and associated with poor survival." (PMID 39857609, 2024). "In summary, our findings indicate that the MYC targeting gene Mad2L1 is potentially related to the dormancy mechanism of prostate cancer." (PMID 35305591, 2022).
liver cancer (4 papers, 2017 to 2021). An epithelial or non-epithelial malignant neoplasm that arises from the liver. "Downregulation of MELK, MAD2L1, and CCNB1 can also inhibit cell cycle progression of liver cancer." (PMID 32420375, 2020).
osteosarcoma (4 papers, 2015 to 2022). A usually aggressive malignant bone-forming mesenchymal neoplasm, predominantly affecting adolescents and young adults. "In a study on osteosarcoma, it was pointed out that RFC3, CDK1, MAD2L1, NDC80, BUB1, etc. jointly participated in the related links of the disease prognosis of osteosarcoma." (PMID 35483337, 2022). "We then performed qRT-PCR to assess the expression of five hub genes (TOP2A, CDK1, MAD2L1, AURKA and RRM2) in human normal osteoblast cells and osteosarcoma cells." (PMID 34156352, 2021). "Subsequently, we performed qRT-PCR to measure TOP2A, CDK1, MAD2L1, AURKA and RRM2 expression in human normal osteoblast cells (hFOB 1.19) and osteosarcoma cells (MG63, U208 and 143B)." (PMID 34156352, 2021). "To determine whether the SAC is engaged in response to DNA damage in mammals, we examined the localization of MAD1 and MAD2L1 after HU treatment in U2OS cells, a human osteosarcoma cell line." (PMID 25898113, 2015).
cervical cancer (3 papers, 2010 to 2023). A primary or metastatic malignant neoplasm involving the cervix. "By analyzing the relationship between the expression level of MAD2L1 and the prognosis of patients with cervical cancer, they found that the expression level of MAD2L1 can be used to predict the prognosis of locally advanced cervical cancer." (PMID 35305591, 2022). "Although MAD2L1, TOP2A, AURKA, and ASPM were reported in various research findings, they may play a remarkable role in the survival of cervical cancer." (PMID 36723760, 2023).
glioma (3 papers, 2011 to 2021). A benign or malignant brain and spinal cord tumor that arises from glial cells (astrocytes, oligodendrocytes, ependymal cells). "RNA levels of eight major mitotic spindle assembly checkpoint (SAC) genes (BUB1, BUB1B, BUB3, CENPE, MAD1L1, MAD2L1, CDC20, TTK) significantly correlated with glioma grade and six also significantly correlated with survival time." (PMID 22022424, 2011).
rhabdomyosarcoma (3 papers, 2021 to 2022). A rare aggressive malignant mesenchymal neoplasm arising from skeletal muscle. "Finally, our experimental results showed that MAD2L1 and CCNB2 were highly expressed in RMS cells and tissues, downregulation of MAD2L1 and CCNB2 inhibited growth of rhabdomyosarcoma cells." (PMID 34838000, 2021).
small cell lung carcinoma (3 papers, 2020 to 2025). Small cell lung cancer (SCLC) is a highly aggressive malignant neoplasm, accounting for 10-15% of lung cancer cases, characterized byrapid growth, and early metastasis. "MAD2L1 has been identified as a potential therapeutic target gene in NSCLC, and could be a promising prognostic biomarker for LUAD and small cell lung cancer, however, there was no similar results in LUSC." (PMID 32411535, 2020).
acute lymphoblastic leukemia (2 papers, 2017 to 2024). Leukemia with an acute onset, characterized by the presence of lymphoblasts in the bone marrow and the peripheral blood. "It was found that almost all of these genes are markers of progenitor B cells, and MAD2L1 and H2AFX in these genes are associated with B-lineage acute lymphoblastic leukemia." (PMID 39498293, 2024).
bladder cancer (2 papers, 2023 to 2026). "A2 specifically binds to the Lys73 site of MAD2L1, activating the cGAS‐STING pathway and thereby inducing apoptosis in bladder cancer cells." (PMID 41168906, 2026). "Next, we performed the survival analysis of these eight genes (ACTA2, CDH1, CCNB1, FLNA, MCM5, MAD2L1, TAGLN and TPM1) in bladder cancer." (PMID 37274283, 2023).
breast invasive carcinoma (2 papers, 2019 to 2023). "There was no significance of DNA promoter methylation between invasive breast cancer and normal breast tissues in 4 upregulated hub genes (MAD2L1, FEN1, CDKN3, CCN2)." (PMID 31777591, 2019).
colorectal adenocarcinoma (2 papers, 2020 to 2021). The most common type of colorectal carcinoma. "We found that among the 12 central genes, CCNA2, MAD2L1, DLGAP5, and AURKA were associated with the overall survival of colorectal adenocarcinoma (P < 0.05), and RRM2 and AURKA were associated with disease-free survival of colorectal adenocarcinoma (P < 0.05)." (PMID 33519906, 2020). "MAD2L1 and BUB1 are critical components of the spindle assembly and are known to be important drivers of carcinogenesis in colorectal adenocarcinoma." (PMID 34070979, 2021).
diabetes mellitus (2 papers, 2021 to 2023). A metabolic disorder characterized by abnormally high blood sugar levels due to diminished production of insulin or insulin resistance/desensitization. "By contrast, the MAD2L1 low-expression group was related to allograft rejection, type 1 diabetes mellitus, and cell adhesion molecules." (PMID 34838000, 2021). "Novel targets include MYO18A, SEC16A, CCNB1, MAD2L1, hsa-mir-4315, hsa-mir-6134, hsa-mir-9500, KIFC3, FBL (fibrillarin), TUBA1A and GFI1B might have crucial biologic functions in the pathogenesis of patients with diabetes mellitus and obesity." (PMID 36837510, 2023).
esophageal carcinoma (2 papers, 2019 to 2023). A primary or metastatic malignant neoplasm involving the esophagus. "However, patients with colon adenocarcinoma and esophageal carcinoma with higher MAD2L1 expression had better prognosis." (PMID 36637946, 2023). "Among these genes, MAD2L1 and CENPF are oncogenes in esophageal carcinoma." (PMID 30716092, 2019).
melanoma (2 papers, 2017 to 2021). A malignant, usually aggressive tumor composed of atypical, neoplastic melanocytes. "A previous PPI network analyses conducted in a whole gene expression dataset of 31 primary melanomas and 52 metastases reported a PPI network in which PCNA, CDK1, MAD2L1, RFC4 and BRCA1 genes showed highest degree centrality values among upregulated genes in metastases." (PMID 28030792, 2017).
mesothelioma (2 papers, 2023). A usually malignant and aggressive neoplasm of the mesothelium which is often associated with exposure to asbestos. "Notably, a recent study showed that BRCA1 in the mesothelioma leads to the co-depletion of MAD2L1 mRNA and protein." (PMID 37174947, 2023). "We had previously reported that BRCA1 contributes to SAC integrity in mesothelioma cells in the presence of the microtubule poison, vinorelbine, through regulating the expression and localization of the SAC components, MAD2L1 and BUBR1, respectively." (PMID 36550359, 2023). "Here, we demonstrated similar roles for BAP1 in controlling MAD2L1 expression and BUBR1 localization to kinetochores in non-drug treated mesothelioma cells." (PMID 36550359, 2023).
pancreatic cancer (2 papers, 2017 to 2021). "Dietary sugar increases the growth of pancreatic cancer cells by increasing MAD2L1 expression." (PMID 34838000, 2021). "Treatment of Capan-2, a pancreatic cancer cell line with autocrine WNT and HH signaling, with BAY ACC002, suppressed the expression of the WNT/β-catenin target genes AXIN2, BIRC5, MAD2L1 and OCT4." (PMID 27750213, 2017).
salivary duct carcinoma (2 papers, 2020 to 2022). An aggressive, high grade adenocarcinoma that arises from the salivary glands. "It has also been demonstrated that MAD2L1 binds with CDC20 and BUB1B and contributes to the abnormal growth of salivary duct carcinoma, despite its participation in signaling transductions." (PMID 36497125, 2022). "Despite the barely known signaling pathways it participated in, MAD2L1 is shown to interact with CDC20 and BUB1B, and correlate with aberrant development of salivary duct carcinoma." (PMID 32795325, 2020).
sarcoma (2 papers, 2019 to 2021). A usually aggressive malignant neoplasm of the soft tissue or bone. "CDK1, KIF11, AURKB, MAD2L1, BUB1B and CCNB2 were highly expressed in sarcoma and were markedly related to worse OS." (PMID 34838000, 2021). "Amongst the eight remaining hub genes, CDC20, CCNB2, AURKB, MAD2L1, CENPE, KIF2C, and PCNA were highly expressed and related with negative prognosis of sarcoma." (PMID 31870357, 2019).
B cell lymphoma (1 paper, 2016). "miR-28 levels were reduced in B cell lymphoma and re-expression of this miRNA leads to impaired cell proliferation through silenced MAD2L1, a component of cell cycle for mitotic spindle coordination." (PMID 27447564, 2016).
clear cell renal cell carcinoma (1 paper, 2016). "In a non-immune cell related cancer, clear cell renal cell carcinoma, transfection with miR-28 mimic was shown to weaken mitotic checkpoint activation and to induce chromosomal instability by targeting MAD2L1." (PMID 27447564, 2016).
COVID-19 (1 paper, 2021). A disease caused by infection with severe acute respiratory syndrome coronavirus 2. "Genes involved in cell cycle, were over-expressed among COVID-19 compared to both HLTY controls and INFL, with a “hill” pattern (e.g. PTTG1, CDC6, MAD2L1, E2F1)." (PMID 34135895, 2021).
ductal breast carcinoma (1 paper, 2021). "An increase in the level of MAD2L1 transcripts is detected in a large number of samples with ductal breast carcinoma." (PMID 34249670, 2021).
Ductal carcinoma in situ (1 paper, 2017). "We thus concluded that Five genes: CDK1, CCNB2, MAD2L1, PPARG, ACACB were finally identified to participate in the regulation and serve as potential diagnosis signatures in in Ductal carcinoma in situ." (PMID 28977921, 2017).
embryonal cancer (1 paper, 2016). A non-seminomatous malignant germ cell tumor characterized by the presence of large germ cells with abundant cytoplasm resembling epithelial cells, geographic necrosis, high mitotic activity, and pseudoglandular and pseudopapillary structures formation. "Meanwhile, MAD2L1 and AURKB were involved in DO terms of type cancer, germ cell cancer, embryoma, and embryonal cancer." (PMID 27610375, 2016).
fibrosis (1 paper, 2022). the formation of excess fibrous connective tissue in an organ or tissue in a reparative or reactive process. "We analyzed the expression of MAD2L1 in lung tissues from control subjects, IPF patients, and mice with bleomycin-induced fibrosis via IHC, qRT-PCR, and Western blot analysis." (PMID 36247080, 2022). "Overall, the present study revealed that MAD2L1 was upregulated in both IPF lungs and the lungs of mice with bleomycin-induced fibrosis." (PMID 36247080, 2022). "We found that MAD2L1 was highly upregulated in alveolar epithelial cells in fibrotic lung tissues from both patients with IPF and mice with bleomycin-induced fibrosis." (PMID 36247080, 2022).
gonococcal infection (1 paper, 2014). "Further, the gonococcal infection upregulated MAD1L1 mitotic arrest deficient-like 1 (encoding the MAD1 protein) by 1.4-fold and downregulated MAD2L1 mitotic arrest deficient-like 1 (encoding the MAD2 protein) by 0.7-fold." (PMID 25460012, 2014).
hepatitis B (1 paper, 2021). "Among them, PTTG1, MAD2L1, CDK1, and NEK2 may be the key prognostic genes of the hepatitis B inflammation and cancer transformation." (PMID 34539726, 2021).
hepatoblastoma (1 paper, 2025). Hepatoblastoma (HB) is a malignant hepatic tumor and is the most common pediatric liver cancer. "So MAD2L1 was selected for further functional validation to determine its feasibility as a potential biomarker for hepatoblastoma." (PMID 40231267, 2025). "This suggests the importance of MAD2L1 in cell cycle regulation in hepatoblastoma, particularly during DNA replication and cell division." (PMID 40231267, 2025). "MAD2L1 exhibits significant potential as both a biomarker for early diagnosis and a therapeutic target in hepatoblastoma." (PMID 40231267, 2025). "The results of ssGSEA analysis further suggest the potential value of MAD2L1 as a prognostic marker in patients with hepatoblastoma." (PMID 40231267, 2025). "To further verify the regulatory effect of MAD2L1 on E2F, we first used the dual-luciferase reporter assay to measure the relative luciferase activity of hepatoblastoma cells co-transfected with siRNA and specific luciferase reporter plasmids." (PMID 40231267, 2025). "This highlights the critical role of MAD2L1 in hepatoblastoma progression." (PMID 40231267, 2025). "Establishing MAD2L1 as a clinically actionable target could lead to personalized treatment strategies and improve outcomes for hepatoblastoma patients." (PMID 40231267, 2025). "Although MAD2L1 has been studied in other types of cancer, its role in hepatoblastoma has not been fully explored, Moreover, MAD2L1 has good performance in AUC value, sensitivity and specificity, indicating that it has high diagnostic value." (PMID 40231267, 2025).
idiopathic pulmonary fibrosis (1 paper, 2022). Idiopathic pulmonary fibrosis (IPF) is a nonneoplastic pulmonary disease that is characterized by the formation of scar tissue within the lungs in the absence of any known cause. "The data suggested that alleviation of mitochondrial damage in alveolar epithelial cells through augmentation of MAD2L1 may be served as a novel therapeutic strategy for a cure of idiopathic pulmonary fibrosis." (PMID 36247080, 2022).
invasive ductal breast carcinoma (1 paper, 2024). The most common type of invasive breast carcinoma, accounting for approximately 70% of breast carcinomas. "Moreover, the expression of KIF2C, PLK1 and MAD2L1 (mitotic arrest deficient 2 like 1) was correlated to reduced overall survival (OS) in invasive ductal breast carcinoma." (PMID 38344808, 2024).